MIR5000 (microRNA 5000)
Synonyms: hsa-mir-5000
Gene: MicroRNA gene on chromosome 2 (75,090,812 to 75,090,914, forward strand). Ensembl gene ENSG00000263909.
Homologues: Orthologues: chimpanzee MIR5000 (100% identical).